ATP6V0A2 (ATPase H+ transporting V0 subunit a2)
Description:
Subunit of the V0 complex of vacuolar(H+)-ATPase (V-ATPase), a multisubunit enzyme composed of a peripheral complex (V1) that hydrolyzes ATP and a membrane integral complex (V0) that translocates protons (By similarity). V-ATPase is responsible for acidifying and maintaining the pH of intracellular compartments and in some cell types, is targeted to the plasma membrane, where it is responsible for acidifying the extracellular environment (By similarity). Essential component of the endosomal pH-sensing machinery. May play a role in maintaining the Golgi functions, such as glycosylation maturation, by controlling the Golgi pH. In aerobic conditions, involved in intracellular iron homeostasis, thus triggering the activity of Fe(2+) prolyl hydroxylase (PHD) enzymes, and leading to HIF1A hydroxylation and subsequent proteasomal degradation.
Synonyms: TJ6; a2; TJ6s; TJ6M; ATP6a2; J6B7; ATP6N1D; Vph1; Stv1; a2V; RTF; ARCL; ARCL2A; WSS
Tractability: Antibody: its Gene Ontology location is reachable by antibodies, with high confidence; UniProt places it where antibodies can reach, with medium confidence; UniProt predicts a signal peptide or a membrane-spanning region; the Human Protein Atlas places it where antibodies can reach. PROTAC: ubiquitination databases record sites on it; its protein half-life has been measured.
Gene: Protein-coding gene on chromosome 12 (123,712,342 to 123,761,755, forward strand). Ensembl gene ENSG00000185344.
Subcellular location: Cell membrane; Endosome membrane
Subcellular location (Human Protein Atlas): Connecting piece; Mid piece; Plasma membrane; End piece; Focal adhesion sites; Principal piece; Vesicles
Pathways (Reactome):
Transport of small molecules: Ion channel transport; Transferrin endocytosis and recycling
Immune System: ROS and RNS production in phagocytes
Signal Transduction: Insulin receptor recycling
Gene Ontology:
Molecular function: protein binding; ATPase binding; proton-transporting ATPase activity, rotational mechanism; proton transmembrane transporter activity
Biological process: cellular response to increased oxygen levels; intracellular iron ion homeostasis; Golgi lumen acidification; immune response; proton transmembrane transport; regulation of macroautophagy; vacuolar acidification
Cellular component: lysosomal membrane; plasma membrane; endosome membrane; Golgi membrane; phagocytic vesicle membrane; proton-transporting V-type ATPase complex; vacuolar proton-transporting V-type ATPase complex; acrosomal vesicle; perinuclear region of cytoplasm; proton-transporting V-type ATPase, V0 domain; vacuolar proton-transporting V-type ATPase, V0 domain
Genetic constraint (gnomAD): Loss-of-function variants: 39 observed, 84.54 expected, observed/expected ratio (o/e) 0.46, 90% interval 0.36 to 0.6. The upper end of that interval is the gene's LOEUF score, 0.6, which puts it in group 2 of 6, group 1 being the genes least tolerant of losing a copy. Missense variants: 812 observed, 976.78 expected, observed/expected ratio (o/e) 0.83, 90% interval 0.78 to 0.88. Synonymous variants: 337 observed, 370.55 expected, observed/expected ratio (o/e) 0.91, 90% interval 0.83 to 1.
Gene-disease validity (ClinGen):
ClinGen rates the evidence that ATP6V0A2 causes each of these diseases.
autosomal recessive cutis laxa type 2A (autosomal recessive): Definitive. An autosomal recessive cutis laxa type II classic type that has material basis in homozygous or compound heterozygous mutations in the ATP6V0A2 gene on chromosome 12q24.
Homologues: Orthologues: chimpanzee ATP6V0A2 (99% identical), macaque ATP6V0A2 (99% identical), dog ATP6V0A2 (95% identical), pig ATP6V0A2 (94% identical), mouse Atp6v0a2 (92% identical), guinea pig ATP6V0A2 (88% identical), zebrafish atp6v0a2b (68% identical), zebrafish atp6v0a2a (66% identical), tropical clawed frog atp6v0a2 (62% identical), Drosophila melanogaster Vha100-3 (36% identical). Paralogues in human: ATP6V0A1 (53% identical), ATP6V0A4 (51% identical), TCIRG1 (49% identical).
Diseases named in the same sentence as ATP6V0A2 in open-access papers:
ATP6V0A2 is named in the same sentence as 34 diseases in open-access papers, as found by Europe PMC text mining. Sharing a sentence is not in itself a finding about the gene and the disease. The quoted sentences say what the papers report.
cutis laxa (8 papers, 2010 to 2024). Cutis laxa (CL) is an inherited or acquired connective tissue disorder characterized by wrinkled, redundant and sagging inelastic skin associated with skeletal and developmental anomalies and, in some cases, with severe systemic involvement. "ATP6V0A2 is a2 subunit of the V-ATPase, and mutations in this subunit are associated with cutis laxa, characterized by loose and inelastic skin and by abnormalities in other connective tissues including the blood vessels and joints." (PMID 39048556, 2024). "Homozygous mutations in ALDH18A1 (or other genes e. g., PYCR1, ATP6V0A2) can result in a heteogenous group of rare diseases characterized by loose or wrinkly skin known as cutis laxa." (PMID 26569114, 2015). "ATP6V0A2-related cutis laxa seizures often appear later in the course of the disease in patients that initially only show a mild developmental delay with speech delay." (PMID 40225911, 2024). "The Atp6v0a2−/− and Atp6v0a2RQ/RQ mouse models both recapitulate the ARCL2A/WSS/ATP6V0A2-CDG phenotype with cutis laxa-like skin changes due to reduced elastin deposition." (PMID 39680136, 2024).
wrinkly skin syndrome (4 papers, 2019 to 2024). "Loss-of-function variants in ATP6V0A2, encoding the trans Golgi V-ATPase subunit V0a2, cause wrinkly skin syndrome (WSS), a connective tissue disorder with glycosylation defects and aberrant cortical neuron migration." (PMID 39680136, 2024). "ATP6V0A2‐related CL, a.k.a. autosomal recessive CL type 2A (ARCL2A, MIM #219200), spans a phenotypic spectrum including the Debré‐type at the severe end and wrinkly skin syndrome (WSS, MIM #278250) at the mild end." (PMID 33275834, 2021).
ovarian carcinoma (3 papers, 2017 to 2024). A malignant neoplasm originating from the surface ovarian epithelium. "The ATP6V0A2 subunit is overexpressed in ovarian cancer, associated with cell membrane driving metastasis, and blocking its action was shown to overcome cisplatin resistance in ovarian cancer." (PMID 35013112, 2022). "Recently, ATP6V0A2 is reported to be implicated in ovarian cancer and breast tumor." (PMID 39048556, 2024).
autosomal recessive cutis laxa type 2 (2 papers, 2015 to 2019). A spectrum of connective tissue disorders characterized by the association of wrinkled, redundant and sagging inelastic skin with growth and developmental delay, and skeletal anomalies. "Interestingly, wrinkled and lax skin, as seen in GO, is also evident in autosomal recessive cutis laxa type 2 (ARCL2), which is caused by mutation of the ATP6V0A2 subunit of the vacuolar ATPase61." (PMID 30631079, 2019).
infertile (2 papers, 2013 to 2020). "The vacuolar ATPase ATP6V0A2 transcripts and proteins are down-regulated in the sperm of infertile men27." (PMID 32409652, 2020). "In summary, Atp6v0a2 protein and mRNA in spermatozoa from infertile men was significantly lower compared to that of normal spermatozoa." (PMID 23936208, 2013).
congenital disorder of glycosylation (1 paper, 2019). Congenital disorder of glycosylation (CDG) is a fast growing group of inborn errors of metabolism characterized by defective activity of enzymes that participate in glycosylation (modification of proteins and other macromolecules by adding and processing of oligosaccharide side chains). "Interestingly, the Golgi-associated protein, ATP6V0A2, is involved in congenital disorders of glycosylation (CDG) because of a pH imbalance in the Golgi apparatus." (PMID 31118204, 2019).
Flavivirus Infections (1 paper, 2025). Infections with viruses of the genus FLAVIVIRUS, family FLAVIVIRIDAE. "Taken together, these results suggest that the ATP6V0A2 subunit was a target of C156-P1 and is primarily responsible for preventing endosomal acidification, thereby inhibiting flavivirus infection." (PMID 41004242, 2025).
glioma (1 paper, 2015). A benign or malignant brain and spinal cord tumor that arises from glial cells (astrocytes, oligodendrocytes, ependymal cells). "This analysis showed that ATP6V1G1 and ATP6V0A2 are frequently over-expressed in gliomas compared to non-neoplastic brain tissues without concomitant up-regulation of other subunits." (PMID 26020805, 2015).
Globozoospermia (1 paper, 2024). Any structural anomaly of the acrosome resulting in a round sperm head. "Several murine and human genetic defects causing globozoospermia affect Golgi proteins involved in acrosome formation, but variants in ATP6V0A2 have not yet been described to affect this process." (PMID 39680136, 2024).
ovarian tumors (1 paper, 2022). "While we previously reported the ability of PHY34 to inhibit lysosomal acidification and reduce ovarian tumors, this work demonstrates PHY34 inhibits the ATP6V0A2 subunit." (PMID 35013112, 2022).
Salmonella Infections (1 paper, 2018). Infections with bacteria of the genus SALMONELLA. "On the other hand, FOXO signaling (TNFSF10, PRKAB1, GADD45B, STK4, STAT3), Salmonella infection (ARPC2, ARPC5L, CCL3L3, CCL4) and lysosome (LAPTM4B, HGSNAT, CD164, ATP6V0A2) pathways were up-regulated, albeit weakly, in the HLA-DR- Teff subset." (PMID 30231065, 2018).
cancer (6 papers, 2015 to 2022). A tumor composed of atypical neoplastic, often pleomorphic cells that invade other tissues. "Overall, our data demonstrate that PHY34 is a promising small molecule for cancer therapy that targets the ATP6V0A2 subunit to induce autophagy inhibition while interacting with CAS and altering nuclear localization of proteins." (PMID 35013112, 2022). "In terms of cancer-driven mutations, the HRSI group has two significant mutations, including HRAS and KLF5, while the LRSI group has three significant mutations, including ATP6V0A2, BSX, and VNN1." (PMID 34504628, 2021).
tumor (5 papers, 2016 to 2023). "PHY34, a synthetic small molecule can target and inhibit the ATP6V0A2 subunit of V‐ATPase and significantly reduce tumor burden." (PMID 37555363, 2023). "Bioinformatics analysis of the Cancer Genome Atlas (TCGA) patient data from different OVCA tumor grades (FIGO grade 1 = 2.1%, n = 42; grade 2 = 22.6%, n = 435; grade 3 = 75.1%, n = 1445) indicate that the expression of the ATP6V0A2 gene correlates with OVCA grade (G1 vs G3, P = 2.02e‐07)." (PMID 32797726, 2020).
infection (3 papers, 2013 to 2025). The state of being infected such as from the introduction of a foreign agent such as serum, vaccine, antigenic substance or organism. "Western blot analyses revealed that the levels of VO subunits ATP6V0A1, ATP6V0A2, ATP6V0A3, and ATP6V0C were significantly decreased in the floxed MEFs after Ad-Cre infection, but V1 subunit ATP6V1E2 was unaffected." (PMID 24223829, 2013).
genetic disorders (1 paper, 2011). "Of these genes, ATP6V0A2 [Ensembl:ENSCAFG00000007234] and EIF2B1 [Ensembl:ENSCAFG00000007434] are of special interest because they are involved in genetic disorders in humans." (PMID 21722374, 2011).
ATP6V0A2 also shares sentences with these, for which no sentence is quoted: breast carcinoma (3 papers); cognitive delay (2); connective tissue disorder (2); glioblastoma (2); abortion (1); acquired lipodystrophy (1); autosomal recessive cutis laxa type 2A (1); breast tumor (1); hair loss (1); hereditary cancer (1); Immunodeficiency (1); liver disease (1); metastatic cancers (1); microcephaly (1); multiple lipomatosis (1); preeclampsia (1); prostate carcinoma (1); sensorineural deafness (1); speech delay (1).